LEP (leptin)
Diseases named in the same sentence as LEP in open-access papers (continued):
Sharing a sentence is not in itself a finding about the gene and the disease.
Obesity (continued). "Although a concomitant increase in CRP and plasma leptin has been observed in obesity, it is not clear whether elevation in CRP is due to acute inflammation or due to adipose tissue expansion or both." (PMID 29910808, 2018). "However, hopes of leptin therapy for common forms of obesity have not been fulfilled, although recombinant human leptin received approval by the U.S. Food and Drug Administration in 2014 for the treatment of generalized lipodystrophy." (PMID 29434574, 2018). "To assess whether obesity was confounding the association between leptin variants and CRC in women, we adjusted our initial logistic regression model for obesity (obese/non-obese BMI)." (PMID 30379922, 2018). "Obesity is characterized by low-grade systemic inflammation with increased levels of C-reactive protein (CRP), proinflammatory cytokines and adipose-derived cytokines, including leptin and adiponectin which may play a role in iron homeostasis." (PMID 30275363, 2018). "When the ob allele of the leptin gene was crossed into the BTBR mouse strain, this BTBR ob/ob mouse developed obesity due to a lack of appetite control and manifested characteristics of type 2 diabetes such as progressive insulin resistance, hyperglycaemia and glucose intolerance." (PMID 30094465, 2018). "Similarly, the correlation observed between leptin levels and 24 h energy expenditure in SD photoperiod in non-obese animals were also abolished in diet-induced obesity." (PMID 30206280, 2018). "We found that the Sprague-Dawley rats did not gain weight after 6 weeks high-fat diet exposure, and did not develop the metabolic hallmarks of obesity that were seen in the Long-Evans rats, such as increased percent body fat and elevated plasma leptin, insulin, and leptin/adiponectin ratio." (PMID 28871134, 2017). "Second, given that leptin levels reflect overall adipose mass, obese people have elevated leptin concentrations, which nevertheless are not able to control obesity by reducing food consumption; in fact, administration of leptin to obese individuals does not lead to weight loss." (PMID 28400989, 2017). "Other pro-obesity related factors such as plasma insulin and leptin were significantly improved, suggesting that in addition to its lipase inhibitory effects; MLE60 positively modulates adipocytic mechanisms through a leptin like activity, to exhibit anti-obesity properties." (PMID 28814950, 2017). "However the influence of the BACHD rats’ obesity and increased leptin levels on their progressive ratio performance is not clear, and conclusive results still have to be obtained." (PMID 28273120, 2017). "However, in most cases of obesity, circulating leptin levels are already high and leptin therapy is not effective." (PMID 28303116, 2017). "However, acute of chronic administration of leptin in humans failed to induce a sustained BP or SNS activity increase, thus the role of leptin in causing sympathetic activation in obesity still need to be fully clarified." (PMID 28966594, 2017). "In obesity, however, it was observed that high levels of leptin do not reduce appetite; a possible explanation may be a state of leptin resistance." (PMID 27598978, 2017). "Interestingly, leptin levels are elevated in LS as compared to lean, age- and gender-matched controls, but not different from obesity-matched controls, suggesting LS that leptin is more closely tied to AT mass." (PMID 28933734, 2017). "In the case of our BMI and obesity studies, chromosomal region 1q25 was previously shown to be related to BMI, obesity, and body fat percentage, whereas FTO was previously identified as a genetic determinant of BMI, obesity, body fat percentage, adiposity, and circulating leptin level." (PMID 28445147, 2017).
Obesity (continued). "Ten biochemical parameters related to diabetes and obesity were measured by a multiplex kit: c-peptide, ghrelin, glucose-dependent insulinotropic polypeptide (GIP), glucagon-like peptide-1 (GLP-1), glucagon, insulin, leptin, plasminogen activator inhibitor-1 (PAI-1), resistin and visfatin." (PMID 28915840, 2017). "However, decreased circulating leptin concentrations following cessation of artificially induced hyperleptinemia in the absence of obesity fails to raise the body weight “set point” in mice." (PMID 28107353, 2017). "As an example, leptin levels are virtually undetectable in the NHP until the middle of the final trimester and parallel the late maturation of adipose tissue; this is evident even in fetal offspring from pregnancies characterized by obesity and hyperleptinemia." (PMID 28993758, 2017). "Therefore, the inhibition of leptin‐induced VSMC proliferation and migration may represent a therapeutic intervention in atherosclerosis after obesity." (PMID 27677429, 2017). "This suggests that leptin could promote cytosolic calcium rise in pathological conditions characterized by hyperleptinemia, such as obesity or hypertension but not in the physiological state." (PMID 28085954, 2017). "These variables also did not change relations of any obesity-related measure with LEP methylation." (PMID 28360946, 2017). "In T2DM patients with common multifactorial obesity, exogenous leptin administration does not seem to improve insulin sensitivity, possibly due to the resistance to leptin action, in a paradigm somehow concordant with what we have found in our observational study." (PMID 28626772, 2017). "In addition, administration of olanzapine and other atypical APDs has been shown to increase blood levels of leptin and ghrelin, suggesting that leptin and ghrelin could also be a link between APD-induced obesity and diabetes." (PMID 29209160, 2017). "Indeed, leptin resistance and the consequent lack of anorexic signaling in the ARC is commonly associated with obesity." (PMID 28303116, 2017). "In neonates, in the absence of leptin or ghrelin, or presence of a premature leptin surge or delayed ghrelin rise, neuronal connections between the relevant hypothalamic brain regions are impaired, leading to metabolic complications and obesity long term." (PMID 29123503, 2017). "However, the changes that occur when leptin resistance develops as a secondary consequence of obesity such as in diet-induced obesity are not compatible with what is occurring in BBS." (PMID 26926121, 2016). "By contrast, in obesity-resistant Lou/C rats, an improved early leptin signaling may be responsible for the lack of deleterious effect of the perinatal high fat diet on glucose tolerance and increased adiposity in response to high fat diet at adulthood." (PMID 27618559, 2016). "Young pre-obese homozygous R299Q γ2 mice exhibited small reductions in plasma leptin compared to WT, with comparable adiponectin, but by 40 weeks displayed hyperleptinemia and hypoadiponectinemia (the latter with reduced WAT expression), consistent with obesity." (PMID 27133129, 2016). "In addition, because lacking normal leptin or a leptin receptor induces obesity in mice, leptin is thought to have an important role in regulating body fat volume and body weight." (PMID 27853416, 2016). "As a possible explanation for these disparate effects, one might speculate that leptin might rather act as a “mediator” of obesity or diabetes related prognostic implications, while omentin-1 exerts effects independent of obesity and diabetes." (PMID 27867249, 2016). "Thus, lower adiponectin levels and elevated leptin levels, proinflammatory cytokines and chemokines, and reactive oxygen species (ROS) and esterified fatty acids have been described in PVAT from both obese patients and animal models of obesity." (PMID 27766104, 2016).
Obesity (continued). "However, the lack of association between prostate enlargement and other proinflammatory cytokines suggests that leptin, in this case, serves as an obesity biomarker rather than an inflammation biomarker." (PMID 27336586, 2016). "Also, we used adiponectin as our adipose-mediated inflammatory marker as these were non-fasting blood samples; however, leptin has been more strongly correlated with obesity-related inflammation and asthma." (PMID 27488495, 2016). "This information made it possible to demonstrate that there were no major differences between the different obesity classes concerning variables that could have influenced the maternal leptin levels." (PMID 27257506, 2016). "Thus, leptin resistance may counteract the expected response to elevated leptin levels and thereby contribute to an increase in MAT during obesity." (PMID 27579023, 2016). "Skeletal muscle activities are inversely related to obesity because obesity accelerates muscle atrophy and decelerates muscle strength via regulating the activities of TNF-α, Ang II, AGEs, Myostatin, exogenous GC, IL-6, I/IGF, vitamin D, Ca2+, estrogen, testosterone and leptin." (PMID 27746742, 2016). "Although some studies have reported that losartan has no anti-obesity effects, the present results shows losartan has anti-obesity effects that decreased body weight, epididymal fat pad weight, adipocyte size and induced development of leptin resistance." (PMID 27322312, 2016). "Furthermore, impairments in leptin-induced STAT3 phosphorylation were demonstrated in a mouse model of diet-induced obesity following a peripheral, but not central injection of leptin." (PMID 27375555, 2016). "In obesity however, elevated leptin does not lead to the expected responses in weight control." (PMID 27716333, 2016). "In obesity leptin levels are already elevated but this does not lead to a suppression of energy intake so a further increase may not be of particular benefit." (PMID 27313541, 2016). "Moreover, there is an inverse link between sleep duration and body mass index, due to the increased levels of leptin and other systemic inflammatory markers during lifetime, which is independent of obesity in adults." (PMID 27610076, 2016). "Our results show that leptin restores the coordinated regulation of fat-specific AQP7 and liver-specific AQP9, a step which might prevent lipid overaccumulation in WAT and liver in obesity." (PMID 26159457, 2015). "Since leptin is directly correlated with obesity and cancer progression, and activates the JNK/STAT3-signaling pathway, we investigated whether leptin and the respective JNK/STAT3-signaling pathway play some role in modulating the expression of mitochondrial or glycolytic genes." (PMID 26472027, 2015). "However, the present study is the first to investigate the occurrence of genetic changes in LEP and LEPR genes in DTC, which might be a likely link between obesity and thyroid cancer." (PMID 25810718, 2015). "However, the molecular mechanisms by which lesser sensitivity to leptin is present in obesity have not yet been defined." (PMID 26064921, 2015). "Furthermore, they observed leptin and insulin resistance, and obesity in SD rats, fed with CD, but not in TGR rats, also received CD." (PMID 26733884, 2015). "The diameter of the small intestinal tumors was significantly higher in all ob/ob mice compared with ob/wt and wt/wt mice (P < 0.001, for both comparisons) (data not shown); thus, the obesity increased the tumor size in spite of lack of growth-promoting leptin, in the ob/ob mice." (PMID 26347815, 2015). "As opposed to the ob/ob mouse, common obesity in humans is characterized not by lack of leptin, but rather by elevated levels of plasma leptin correlated with fat mass and BMI, representing a form of leptin resistance." (PMID 26347815, 2015).
Obesity (continued). "Other indirect mechanisms (in the presence of obesity) include hyperinsulinemia, increased leptin and nonesterified fatty acids (NEFAs) release from excess visceral fat, and reduced baroreceptor sensitivity and activation of the hypothalamic-pituitary-adrenal axis." (PMID 26064978, 2015). "However, the effects of obesity on stroke outcome in obese ob/ob mice are not reversed by leptin administration and are therefore likely to be due to factors associated with adiposity and not leptin deficiency." (PMID 26239227, 2015). "Leptin is a hormone produced by adipose tissue and functions to stimulate glucose uptake and control energy expenditure by facilitating fatty acid oxidation and preventing lipid accumulation through activating AMP kinase and therefore serves as another indicator of diabetes and obesity in our study." (PMID 26770982, 2015). "Thus, in obesity the effects of leptin on food intake are weaker than in the lean state and this provided an explanation as to why in obesity, food intake was not reduced as expected given the markedly elevated plasma levels of leptin." (PMID 26617526, 2015). "The normal physiological effect of leptin on the regulation of TNF-α expression seems to be suppressive, but the hyperleptinemic condition and leptin resistance may both contribute to the rise of TNF-α in the adipose tissue in obesity." (PMID 25762868, 2015). "To interrogate FGF21 pharmacology in a different species and confirm dependence on the leptin pathway on metabolic endpoints such as BW, glycemic control, we used Zucker fatty rats Strain 185 Crl:ZUC-Leprfa27 which lack the leptin receptor and develop obesity and hyperphagia." (PMID 26153793, 2015). "Interestingly, in states of obesity despite a paradoxical impairment of the satiety response, leptin resistance does not extend to leptin mediated endothelial dysfunction." (PMID 25650072, 2015). "Additionally, in these rats, postnatal leptin treatment of offspring from normally-nourished mothers programmes their male offspring to develop obesity in later life, while there is no comparable effect in their female offspring." (PMID 24447410, 2014). "In this study, we investigated strictly nonoverweight women requesting a procedure of assisted reproduction and excluded both overweight and obese women to rule out potential confounding effects of overweight and obesity on leptin and/or visfatin levels and fertilization rates." (PMID 24895638, 2014). "In the leptin analysis, however, the percentage of measurable samples increased with increasing obesity so that analysis by non-parametric rank could be performed without introducing bias." (PMID 24915044, 2014). "Alternatively, obesity itself or its metabolic consequences might explain the phenotype of these animals independent of leptin signaling." (PMID 25232724, 2014). "It is not known whether high plasma levels of leptin, obesity or diabetes per se is the culprit for inducing the observed SAN dysfunction or the reduced autonomic nerve density." (PMID 25113792, 2014). "Nonetheless, overweight and obesity are often, but not always, associated with PCOS, and adipokines, including leptin and visfatin, might also be involved in the pathogenesis of this disease." (PMID 24895638, 2014). "However, elevated saturated FA is sufficient to induce lipotoxic stress in the hypothalamus and attenuate responses to insulin and leptin negative feedback, contributing to dietary-induced obesity (DIO) and attendant metabolic dysfunction." (PMID 25541737, 2014). "However, leptin resistance and obesity do not always go hand-in-hand; leptin resistance can occur in the absence of obesity." (PMID 25211467, 2014). "Noteworthy, leptin levels predict MetS development independent of obesity." (PMID 24741591, 2014).
Obesity (continued). "Furthermore, prospective and interventional studies assessing changes in both plasma leptin levels and FMD are warranted to clarify whether plasma leptin levels are predictive of vascular endothelial function in patients with obesity and T2D." (PMID 24410779, 2014). "Moreover, elevated leptin levels in PVAT promote neointima formation independent of obesity and systemic hyperleptinemia." (PMID 24307898, 2013). "However, expression of hypothalamic Socs-3 did not rise with increasing obesity and leptin levels, as measured 2, 6, and 9 wk p.i.." (PMID 23554574, 2013). "No discovery has had a greater impact on obesity research than that of leptin in 1994." (PMID 23092275, 2013). "Although Ksr2 is expressed in areas of the hypothalamus known to be involved in mediating leptin’s effects on food intake, such as the arcuate nucleus, previous studies performed in Ksr2−/− mice did not convincingly link leptin and melanocortin pathways to the obesity phenotype." (PMID 24209692, 2013). "Leptin levels were also similar in both genotypes of mice fed the LFD and incremented to a similar extent with HFD feeding, suggesting that the susceptibility to obesity of Rag2−/−xT-bet−/− mice was no different from that of Rag2−/− mice." (PMID 23562076, 2013). "Taking together, leptin replacement therapy could be therapeutic opportunities not only for obesity and diabetes, but also for obesity-related depression and anxiety." (PMID 23579596, 2013). "In ganglioside-depleted POMC neurons, neither PStat3 nor PIP3 formation is increased by peripheral leptin injections, strongly suggesting that defects in both pathways may contribute to partial failure of obesity prevention." (PMID 23554574, 2013). "Body mass, body fat mass and serum leptin level significantly decreased in food-restricted hamsters, and increased when the restriction ended, showing a short “compensatory growth” rather than over-weight or obesity compared with ad libitum controls." (PMID 23372694, 2013). "If these neuropeptide Y receptors are not sensitive to the effects of leptin, obesity can result." (PMID 23544116, 2013). "Thus, chronic nutrient excess and elevations in circulating leptin do not appreciably determine global hypothalamic Nnat expression, and hypothalamic Nnat expression is not perturbed in this model of obesity." (PMID 23527188, 2013). "This may suggest that serum leptin concentration is an important predictor of insulin resistance and other metabolic risks irrespective of obesity levels." (PMID 23349940, 2013). "In DIO rats, reduced central leptin sensitivity seems to partially explain their propensity to develop obesity under a high energy diet, since both NPY mRNA expression and food intake were poorly modulated after 4 weeks of food restriction and intracerebroventricular leptin injection, respectively." (PMID 24039946, 2013). "We will then discuss regulation of the nonneuronal leptin system in obesity." (PMID 22530983, 2012). "The negative effects of leptin on bone may predominant over the positive ones in obesity when leptin resistance occurs or when the serum leptin concentration rises above a certain threshold." (PMID 22518129, 2012). "Studies have shown that a reduction of 5–10% body weight is sufficient to significantly improve many of the known obesity-related blood biochemistry parameters, including hyperlipidemia, insulin and leptin resistance, and increased circulating nonesterified fatty acids (NEFA)." (PMID 21904565, 2012). "In contrast, low sOb-R levels, although having no direct influence on leptin action, could serve as one potential indicator for the development of a leptin resistant state in obesity." (PMID 22545089, 2012). "Therefore, it was appropriate to investigate whether leptin levels could correct for the disparity between DXA and BMI and be used to create a more accurate measure of obesity." (PMID 22485140, 2012).